CAV1 (caveolin 1)
Diseases named in the same sentence as CAV1 in open-access papers (continued):
Sharing a sentence is not in itself a finding about the gene and the disease.
renal cell carcinoma (15 papers, 2008 to 2024). "Note, however, that the role of CAV1 in association with miR-203 in cancer has only been elucidated in renal cell carcinoma." (PMID 36233075, 2022). "Although the role of Cav-1 plays in cancer is controversial, it is widely confirmed that overexpression of Cav-1 in renal cell carcinoma is associated with poor disease-free survival and metastasis." (PMID 26066055, 2015). "We previously reported that tumour-associated caveolin-1 is a potential biomarker in renal cell carcinoma (RCC), whose overexpression predicts metastasis following surgical resection for clinically confined disease." (PMID 18283322, 2008). "Silencing of cav-1 has been evidenced to enhance doxorubicin-induced apoptosis and reduced lung metastasis in human renal cell carcinomas." (PMID 29522490, 2018). "The clinical prognostic value of the upregulation of Cav-1 in renal cell carcinoma (RCC) has been clarified." (PMID 25202343, 2014). "The aim of this study was to elucidate the caveolin-1 (CAV1) protein expression in renal cell cancer (RCC) and to determine its potential prognostic relevance." (PMID 22152020, 2011). "Subsequently, by knocking down Bnip3, Cav-1, or Gsn in renal cancer/renal progenitor cell hybrid organoid models, the research team further validated the roles of these genes in renal organogenesis and renal cell carcinoma development." (PMID 39600908, 2024). "Moreover, silencing of the cav-1 gene enhanced doxorubicin-induced apoptosis and reduced lung metastasis in human renal cell carcinoma." (PMID 29522490, 2018). "However, a number of clinicopathologial studies have shown a positive correlation between CAV1 over expression and advanced renal cell cancer, metastasis and poor prognosis." (PMID 22152020, 2011).
asthma (14 papers, 2013 to 2024). "Still, cav-1/caveolae are involved in modulatory processes at this level, which shall be considered in settings such as bronchial hyperreactivity being associated with common airway diseases." (PMID 28555112, 2017). "Our results suggest that the development of antigen-induced airway obstruction and hyperresponsiveness is associated with caveolin-1 expression in airway smooth muscle in a guinea pig model of asthma." (PMID 25977751, 2015). "Complete loss of caveolae and Cav‐1 in airways and vasculature is thought to occur in inflammatory lung diseases such as chronic obstructive pulmonary disease (COPD), asthma, and inflammation‐induced lung injury." (PMID 32508059, 2020). "Nevertheless, a marked decrease in caveolin-1 and caspase 3 was observed in the pulmonary vascular smooth muscle of asthma model compared with controls." (PMID 25977751, 2015). "In contrast, increased levels of caveolin-1 are found in the airway smooth muscle of antigen-challenged in mice and the lungs of guinea pigs subjected to an asthma model." (PMID 25977751, 2015). "In asthma, a shortage of caveolin-1 has been observed in the airways of asthmatic patients." (PMID 25977751, 2015). "In addition, although the asthma model induced a strong caveolin-1 downregulation in vascular smooth muscle accompanied by myocyte proliferation, this phenomenon did not induce pathophysiological consequences such as changes in arterial pressure." (PMID 25977751, 2015). "In the current study, we determined the relationship between caveolin-1 expression and the pathophysiological characteristics of asthma and found that caveolin-1 expression increases in airway smooth muscle and that this increase is related to antigen-induced obstruction and hyperresponsiveness." (PMID 25977751, 2015). "In this murine model, we identified an increase in subepithilial thickening as the main contributor of AHR in Cav1-/- mice, but because asthma is a heterogeneous disease, other cellular components may still play an important role in airway remodeling and AHR." (PMID 24138138, 2013). "GATA6 exhibits an inverse correlation with the expression of Caveolin-1 in mouse models of asthma and silencing of GATA6 upregulates Caveolin-1 expression." (PMID 36918760, 2023). "Diminished Cav1 was also observed in patients with chronic obstructive pulmonary disease (COPD), asthma and cystic fibrosis." (PMID 34678949, 2021). "We evaluated the relationship between caveolin-1 expression in airway smooth muscle (ASM) and antigen-induced airway responsiveness and obstruction in a guinea pig asthma model." (PMID 25977751, 2015). "Our data suggest that caveolin-1 expression in ASM has a crucial role in the development of antigen-induced airway obstruction and hyperresponsiveness in a guinea pig asthma model." (PMID 25977751, 2015). "To our knowledge, we provide the first evidence on the role of caveolin-1/VEGFR2 on VEGF-induced RhoA activation and MUC5AC upregulation in bronchial epithelial cells, suggesting an effective therapeutic target in inflammatory diseases such as asthma." (PMID 31831011, 2019).
Hypercholesterolemia (14 papers, 2014 to 2025). An increased concentration of cholesterol in the blood. "A synergistic effect between eNOS and Cav-1 polymorphisms on IS risk elevation was significantly influenced by alcohol drinking, heavy cigarette smoking (P-trend<0.01), and hypercholesterolemia (P-trend < 0.001)." (PMID 28346478, 2017). "Risk elevation of an LAA stroke in individuals with the eNOS 894Asp variant genotype in combination with Cav-1 polymorphisms stratified by hypercholesterolemia, alcoholism, or heavy cigarette smoking." (PMID 28346478, 2017). "Several studies have indicated that CAV1 genetic variations might interact with other risk factors, including dietary intake of fatty acids, suggesting a positive association between CAV1 and hypercholesterolemia." (PMID 36338969, 2022). "First, the cholesterol-induced disruption of CAV1-mediated lipid rafts (evidenced by SM(d18:2/16:0) accumulation) provides a molecular basis for altered signaling fidelity in hypercholesterolemia." (PMID 40806239, 2025). "Treatment of radioresistant cells with statins, drugs used worldwide for the treatment of hypercholesterolemia, significantly attenuated the Akt1/Cav1 signaling and radioresistance mechanisms through increased cell apoptosis." (PMID 38473215, 2024). "In the present study, we investigated the role of CAV-1 in hypercholesterolemia-induced oxidative damage to the kidneys." (PMID 27124120, 2016). "We demonstrate that diet-induced hypercholesterolemia promotes orthotopic xenograft PC-3 cell metastasis, concomitant with elevated expression of caveolin-1 and IQGAP1 in xenograft tumor tissues." (PMID 25924234, 2015). "We performed Western blotting of both xenograft tumor and cell lysates to determine the effect of hypercholesterolemia on the expression of level of caveolin-1 and IQGAP1." (PMID 25924234, 2015). "We investigated the effects of CAV-1 on mitochondrial biogenesis and antioxidant enzymes in hypercholesterolemia-affected target organs." (PMID 24475013, 2014). "The connection between Cav-1, lipid uptake and endothelial stiffening in vivo is consistent with our findings that genetic deletion of Cav-1 abrogates endothelial stiffening induced by feeding mice a high fat diet, a model of mild hypercholesterolemia." (PMID 36280774, 2022). "However, in long-term hypercholesterolemia, low renal CAV-1 expression and high renal superoxide activity were observed." (PMID 27124120, 2016). "Moreover, CAV-1 attenuated hypercholesterolemia-induced changes in mitochondrial morphology and biogenesis and preserved mitochondrial respiratory function." (PMID 27124120, 2016). "Cav-1 ameliorates nephrotic damage in a rabbit model of cholesterol-induced hypercholesterolemia." (PMID 27124120, 2016). "Therefore, molecular evidence of the interaction between eNOS and Cav-1 polymorphisms, such as 14713A, T29107A and 12759A alleles, on risk predisposition in LAA strokes in carriers who have hypercholesterolemia should be required to provide support in justifying our current association reports." (PMID 28346478, 2017). "Therefore, CAV-1 may exert antioxidant effects by enhancing NO expression in hypercholesterolemia." (PMID 27124120, 2016). "Down-regulation of caveolin-1 or IQGAP1 in PC-3 cells reduced migration and invasion in vitro, and hypercholesterolemia-induced metastasis in vivo." (PMID 25924234, 2015). "Taken together, these results suggest that IQGAP1 and caveolin-1 potentiate PC-3 metastasis, and that the elevation of IQGAP1 levels in hypercholesterolemia plays an important role in metastasis." (PMID 25924234, 2015). "We further demonstrate the involvement of two proteins, caveolin-1 and IQGAP1 in hypercholesterolemia-induced xenograft tumor metastasis in vivo." (PMID 25924234, 2015).
Hypercholesterolemia (continued). "Therefore, AP-CAV-1 treatment resulted in significantly lower expression of electron transport chain (ETC) complex I–V proteins (−0.76-fold, P < 0.05), suggesting that CAV-1 treatment reserves mitochondrial respiratory function in animals with hypercholesterolemia." (PMID 27124120, 2016). "Our results show that hypercholesterolemia increases the level of both proteins in the DRF fraction, but it is not clear whether caveolin-1 and IQGAP1 actually co-localize to the same membranes." (PMID 25924234, 2015).
metastatic carcinoma (14 papers, 2011 to 2025). A carcinoma which has spread from the original site of growth to another anatomic site. "In metastatic cancers and carcinomas, CAV1 interaction with AGO2 in the plasma membrane are widely distributed and abundant as compared with primary tumors." (PMID 40863728, 2025). "Consistent with the results of cultured cancer cells and tumor xenografts, this increase in EV miRNA-3613-3p in patient plasma was positively correlated with increased Ago2/CAV1 interaction in human metastatic carcinomas." (PMID 38649663, 2024). "Although CAV1 inhibits migration through its scaffolding domain in HeLa cells, CAV1 increases migration via several signaling pathways in metastatic cancer cells." (PMID 32458269, 2020). "In metastatic cancer cells, activation of the small GTPase Rac-1, required for CAV1 to promote cell migration and invasion, involves upstream activation of Rab-5, another small GTPase." (PMID 32152405, 2020). "In contrast, a growing body of evidence indicates that caveolin-1 is up-regulated in several multidrug-resistant and metastatic cancer cell lines and human tumor specimens." (PMID 21471610, 2011). "Interestingly, caveolin-1 is overexpressed in other metastatic carcinoma cells where it promotes growth and resistance to anoikis." (PMID 32033410, 2020). "Additionally, caveolin-1 seems also to impact on FC stability, as shown in metastatic cancer cells and MEFs." (PMID 22505999, 2012). "Thus, we evaluated the effect of caveolin-1 on FA turnover in metastatic cancer cells by transfection with GFP-vinculin followed by time-lapse videomicroscopy analysis." (PMID 22505999, 2012). "Interestingly, phosphorylation of CAV1 on Y14 appears to be necessary to induce this CAV1-dependent metabolic switch, which points towards the importance of both CAV1 expression and Y14-phosphorylation for maintenance of the metabolic phenotype in metastatic cancer cells." (PMID 35740528, 2022). "Cav1 gradually increases during epithelial transformation into primary SCC and decreases afterwards in metastatic carcinoma." (PMID 34207120, 2021). "Expression of the scaffolding protein Caveolin-1 (CAV1) enhances migration and invasion of metastatic cancer cells." (PMID 29340103, 2017). "Bearing this in mind, the aim of this study was to evaluate the effect of CAV1 expression on the metabolism of metastatic cancer cells lacking E-cadherin and how Tyr-14 phosphorylation participates in these events." (PMID 35740528, 2022). "Here, we studied the effect of CAV1 on metastatic cancer cell metabolism and observed that Y14CAV1 phosphorylation induces mitochondrial dysfunction and the Warburg effect, thereby increasing ROS levels, which inhibit PTP1B to augment further pY14-CAV1 levels." (PMID 35740528, 2022).
squamous cell carcinoma (14 papers, 2014 to 2025). A carcinoma arising from squamous epithelial cells. "In contrast to these findings, others associated a low expression of Cav-1 in tumor cells of squamous cell carcinoma of the head and neck with an increase in cell motility and invasion." (PMID 33774714, 2021). "Interestingly, several genes found to be differentially enriched in the BC-2 subpopulation, such as Tppp3, Tnfrsf12a, and Cav1 have been associated with severity or aggressiveness of squamous carcinoma in various organs." (PMID 36178196, 2022). "Here the expression patterns of CAV1 were analyzed in a retrospective cohort (n=43) of penile squamous cell carcinomas (SCC)." (PMID 33868995, 2021). "Previous reports support the evidence that in squamous cell carcinoma overexpression of CAV-1 is directly related to the disease progression, in this differing to other tumours." (PMID 30917536, 2019). "In our study, the expression of CAV1 was decreased in adenocarcinoma and squamous cell carcinoma, which was congruent to the expression of LINC81507." (PMID 31296840, 2019). "We investigated the mRNA expression of flotillin-1, stomatin, and caveolin-1 using real-time PCR in 22 paired (tumor and corresponding normal tissue) samples of adenocarcinomas and 26 paired samples of squamous cell carcinomas." (PMID 24533441, 2014). "In addition, GM3 overexpression has been shown to be located on lipid rafts complexed with EGFR and caveolin-1 in human squamous carcinoma cells inhibiting EGFR activation." (PMID 31578452, 2019). "Rh2, a major bioactive constituent of Panax ginseng, a traditional medicine, inhibited lipid raft-mediated Akt signalling, which affected the dynamics of CAV1 and GM1 in an epidermoid carcinoma cell line, A431." (PMID 34428960, 2021). "By contrast, CAV1 inhibited the autophosphorylation of EGFR and PDGFR in epidermoid carcinoma and fibroblasts, respectively." (PMID 34428960, 2021). "High Cav-1 expression in tumor cells was observed in 52% (38/73) of squamous cell carcinomas (SQCs) and 33% (45/138) of non-SQCs." (PMID 31297035, 2019). "Indeed, the genes ACTG1, CAV1, MYLK, and PAK were also found to be deregulated in a transcriptomic analysis of epidermoid carcinoma cells A431, indicating that BCL6 modulates the invasion capacity of physiological and malignant components through similar molecular mechanisms." (PMID 33182312, 2020). "We were not able to examine caveolin-1 expression in other cell lines, However, in TCGA data analysis we found CAV1 amplification in both lung cancer adenocarcinoma and squamous cell carcinoma and due to multicopy number variation caveolin-1 protein expression is elevated." (PMID 34762666, 2021).
cardiomyopathy (13 papers, 2009 to 2025). A disease of the heart muscle or myocardium proper. "The mice with deficient in both Cav-1 and Cav-3 develop more severe cardiomyopathy compared to the mice with deficient in either Cav-1 or Cav-3." (PMID 40041164, 2025). "Mice deficient in caveolin-1/3 develop a cardiomyopathy reminiscent of Chagas heart disease, and evidence supports that the down regulation of caveolin may support cellular infection." (PMID 24312535, 2013). "We identified 250 down-regulated genes, with many of them known to be important for heart development, such as Ttn, Cav1, Bmp5, and Actc1; Go Ontology (GO) analysis showed that these genes are important for maintaining normal heart function or are closely implicated in cardiomyopathies." (PMID 31541101, 2019). "Caveolin-1/caveolin-3-double knockout mice develop severe cardiomyopathy, compared to that in caveolin-1-knockout, caveolin-3-knockout, or wild-type mice." (PMID 32257548, 2020). "Other studies revealed that in addition to ERK1/2 signaling, the negative regulation of eNOS by caveolin-1, which results in constitutive hyperactivation of the nitric oxide pathway in caveolin-1-knockout mice, is also involved in the development of severe cardiomyopathy and impaired pump function." (PMID 32257548, 2020). "Cav3−/− mice also develop cardiomyopathy with ERK activation in the heart, and Cav1 and Cav3 double-knockout mice exhibit a severe cardiomyopathic phenotype compared with Cav1−/− mice and Cav3−/− mice." (PMID 27612189, 2016). "The important role of caveolae in cardiac function has been highlighted by the fact that animal models lacking caveolin-1 and -3 display severe cardiomyopathy characterized by an increase in ventricular wall thickness, hypertrophy, and a decrease in fractional shortening." (PMID 35514336, 2022). "We showed that NOS3, CAV1 and SIRT1 are expressed in the cardiomyopathies as well as other non-cancer and non-heart related diseases." (PMID 36385157, 2022).